LEP (leptin)
Diseases named in the same sentence as LEP in open-access papers (continued):
Sharing a sentence is not in itself a finding about the gene and the disease.
Abdominal obesity (continued). "After considering changes in WC, we found no significant changes in leptin levels in individuals with no increase in WC after smoking cessation but a significant increase in leptin levels in individuals with abdominal obesity." (PMID 30086171, 2018). "Leptin levels and FLI were positively associated with the most cognitive domains and their Waist-to-Hip Ratio (WHR), a traditional index of central obesity." (PMID 29867443, 2018). "At least in individuals with abdominal obesity after smoking cessation, increased leptin levels are probably affected more by weight gain after smoking cessation than by changes in smoking status." (PMID 30086171, 2018). "Adiponectin levels were significantly lower, while leptin levels were significantly higher in subjects with abdominal obesity." (PMID 28421328, 2017). "In contrast, the main mechanism of central obesity promoting TNBC progression is the disturbance of the ‘insulin-leptin-adiponectin’ axis." (PMID 27247890, 2016). "The proposed association between central obesity (W:H ratio) and CD4 can be explained by leptin (secreted by adipocytes) aiding in the proliferation of CD4+ T-cells." (PMID 25887844, 2015). "It is known that leptin levels reflect the amount of adipose tissue in the body, and hyperleptinemia is common in general and abdominal obesity." (PMID 24981337, 2014). "One case observed a significant statistical correlation with serum leptin levels and fat mass; abdominal obesity and visceral fat area were positively correlated with serum leptin level." (PMID 25251414, 2014). "For this case, the mean value of leptin in subjects with abdominal obesity was 1141.8 ± 343.6 ng/mL, while it decreased to 858.3 ± 419.6 ng/mL in individuals exhibiting a normal waist perimeter." (PMID 23986664, 2013). "A possible mechanism by which central obesity promotes glomerular damage and induces microalbuminuria is through decreasing serum adiponectin and increasing serum leptin levels." (PMID 23251329, 2012). "For instance, sOB-R was negatively associated with central obesity, elevated triglyceride and reduced HDL-C, whereas leptin was only associated with hypertriglyceridemia in multivariate regression including FMI." (PMID 21347230, 2011). "Leptin/NPY ratio and leptin/BMI ratio was also higher in the central obesity group and there was a more significant difference compared with controls." (PMID 17721641, 2007). "In subjects with central obesity, propolis can reduce leptin levels." (PMID 41245948, 2025). "In addition, central obesity disrupts the stability of the hypothalamic-pituitary-ovarian axis by affecting the secretion of leptin, reactive oxygen species and other adipokines, which further exacerbates metabolic and reproductive abnormalities." (PMID 40084142, 2025). "It has been found that excessive FFAs can lead to a decrease in leptin protein and mRNA levels, suggesting that in cases of abdominal obesity, excessive FFAs may reduce leptin expression, leading to fat deposition in hepatocytes." (PMID 39683601, 2024). "According to a meta-analysis, people with gallstones have higher levels of leptin, which may point to a crucial role of central obesity in the development of gallstones." (PMID 38238700, 2024). "For LEP GG genotype we found the lowest average weight and BMI suggesting a leaner body composition and the lowest waist circumference and waist/hip ratio indicative of lesser central obesity." (PMID 39203789, 2024). "However, other expressions of body fat, strongly associated with circulating leptin levels, were considered in multivariate models (i.e., BAI, BMI, WC or their “condition”—excess body weight and abdominal obesity)." (PMID 37217748, 2023). "In a quasi-experimental study, subjects with central obesity and normal weight were collected to determine whether honey and propolis can decrease leptin levels in patients with central obesity." (PMID 37063322, 2023).
Abdominal obesity (continued). "The study found that honey and propolis can reduce leptin levels in participants with central obesity, indicating that these bee products may become dietary supplements for patients with central obesity." (PMID 37063322, 2023). "Leptin/adiponectin imbalance might mediate the increased risks of developing T2DM and cardiovascular diseases(CVDs) associated with abdominal obesity." (PMID 34446063, 2021). "Defects in leptin action may promote central obesity by increasing energy intake and decreasing energy expenditure." (PMID 34987473, 2021). "Sleeping for less than 7 h can provoke mutual changes in circulating leptin and ghrelin levels, resulting in high ghrelin and low leptin levels, increasing appetite, caloric intake, and lowering energy expenditure, facilitating an increase in central obesity, one of the main components of MetS." (PMID 34670597, 2021). "Our results highlighted the relationship among leptin, central obesity, and severity of CAN." (PMID 33076921, 2020). "This raises the possibility that leptin might mediate the relationship between central obesity and the severity of cardiovascular autonomic neuropathy (CAN) in patients with well-controlled T2DM and prediabetes." (PMID 33076921, 2020). "The results suggest that increased pulse wave velocity associated with leptin do not depend on abdominal obesity." (PMID 32198598, 2020). "Thus, we would argue that shifts in the leptin/adiponectin ratio in men were primarily due to their central obesity." (PMID 30735826, 2019). "Interaction effects between central obesity and the clustering of the other 4 MetS cardiometabolic risk factors were found for TNF-α (Wald chi square = 5.47, P = 0.019), leptin (Wald chi square = 4.92, P = 0.027) and adiponectin (Wald chi square = 9.17, P = 0.002)." (PMID 30114249, 2018). "Consistently, our results also indicate the interaction effect between central obesity and the clustering of 4 MetS risk factors on the adiponectin: leptin ratio (P = 0.016) (data not shown)." (PMID 30114249, 2018). "Therefore, this study sought to determine the role of adipokines (adiponectin, plasminogen activator inhibitor-1, leptin, and tumor necrosis factor-α) in hypertensive Hong Kong Chinese women with central obesity." (PMID 29636702, 2018). "Our analyses showed significant main effects of central obesity on circulating leptin and PAI-1." (PMID 29636702, 2018). "The aim of the present study was to investigate the serum levels of selected adipokines (adiponectin, leptin and resistin) in various types of dementia and mild cognitive impairment in relation to abdominal obesity—the most important feature of metabolic syndrome." (PMID 28421328, 2017). "The comparison of investigated adipokines levels between subjects with and without abdominal obesity revealed significant differences concerning adiponectin and leptin but not resistin levels, both in all-cause dementia and controls." (PMID 28421328, 2017). "In stratified analyses, the association between leptin and risk of frailty was similar in those with or without abdominal obesity, and in those with body fat percentage above or below the sample median." (PMID 28400989, 2017). "The statistically significant lower level of leptin in all-cause dementia in comparison with controls was found only in those without abdominal obesity [4.32 ng/mL (2.33–8.09) vs. 5.81 ng/mL (2.98–11.09), p = 0.042]." (PMID 28421328, 2017). "There is renewed use of antidiabetic agents such as thiazolidinediones and metformin that have modest effects on abdominal obesity, as well as leptin analogs to determine whether use of these agents may ameliorate cognitive decline in individuals with T2D." (PMID 26560876, 2015). "↓ PWV, HOMA, TAG, uric acid, abdominal obesity and leptin, ↑ adiponectin." (PMID 26132993, 2015).
Abdominal obesity (continued). "Indeed, leptin was significantly correlated with increased BMI (r = 0.4173, p = 0.0001), central obesity (r = 0.4678, p < 0.0001), and body fat percentage (r = 0.3583, p = 0.0010) (respectively)." (PMID 23986664, 2013). "Interestingly, serum values of leptin still showed a significant elevation when examining in subjects with abdominal obesity." (PMID 23986664, 2013). "Increased central obesity normally leads to increased leptin that could be responsible for the decrease in testosterone level previously reported among this population via functional leptin receptor isoform on Leydig cells." (PMID 23895401, 2013). "In particular, the altered pattern of adipocytokine secretion characterizing central obesity—that is, reduced adiponectin and elevated levels of leptin, resistin, TNFα, and IL-6—increases the production of superoxide anion (O2−), that interferes with NO availability, thus reducing vasodilation." (PMID 20652043, 2010). "Thus, interactions between angiotensin II and adiponectin/leptin imbalances may be important mediators of the T2DM and cardiovascular disease risks associated with abdominal obesity." (PMID 37571250, 2023). "Thus, the association of WHtR with BP and arterial stiffness may be more related to abdominal obesity itself than high level of circulating leptin." (PMID 36973671, 2023). "The results of our study may suggest that leptin and resistin levels are strongly correlated with abdominal obesity, and their secretion is upregulated in increased abdominal adiposity among PCOS women, whereas hypoadiponectinemia is associated with PCOS diagnosis independently of abdominal obesity." (PMID 37630842, 2023). "Thus, our results highlighted the relationship among leptin, central obesity, and severity of CAN." (PMID 33076921, 2020). "Similarly to leptin the L/A ratio depended only on the presence of abdominal obesity, but not dementia status and the significant interaction between dementia status and abdominal obesity was shown (p = 0.007)." (PMID 28421328, 2017). "A fixed excess of leptin was associated with increasing risk for all-cause and cardiovascular mortality in patients with abdominal obesity but had the opposite effect in those without abdominal obesity." (PMID 28333114, 2017). "So, because of leptin resistance, CCS exposed to cranial irradiation have a higher BMI, fat mass, and central obesity." (PMID 38254811, 2024). "Among them, adiponectin, leptin, TNF-α, Factor D (adipsin), lipocalin-2 (NGAL), Serpin E1 (PAI-1), and CXCL8 (IL-8) were confirmed to have a positive correlation with central obesity (defined as WC)." (PMID 36768360, 2023). "In our study, individuals with abdominal obesity (n = 203) showed higher levels of BMI, total cholesterol, LDL-C, TG, and leptin (p < 0.05), which correlates with Ragino Yu.I." (PMID 37888112, 2023). "Among women with a BMI of 20 to < 25, participants with leptin > 97.5th had significantly higher levels of HOMA-IR, UA and a higher proportion of central obesity (WC > 85 cm) compared to participants with leptin levels of 2.5th to ≤ 97.5th." (PMID 35941672, 2022). "A cross-sectional analysis from the Baltimore Longitudinal Study of Aging which included 749 patients (mean age 67 years) investigated adiponectin, leptin and resistin in relation with carotid–femoral PWV and abdominal obesity." (PMID 34202323, 2021). "Leptin and leptin to adiponectin ratio was the strongest adipocytokine predictor of serum hepcidin in males only, an effect which may potentially be attributed to the effect of central obesity and leptin on liver function and subsequent hepatic hepcidin expression." (PMID 34063273, 2021). "The result showed that central obesity lowers adiponectin plasma levels via increasing proinflammatory adipokines, such as TNF-alpha, leptin, and IL-1β." (PMID 33946540, 2021).
Abdominal obesity (continued). "In addition to adiponectin, we also observed relatively higher leptin in centrally obese subjects with the clustering of 4 MetS risk factors compared to the subjects with only central obesity, with the clustering of 4 MetS risk factors or without any MetS risk factors." (PMID 30114249, 2018). "The main effects of central obesity were observed on PAI-1 (Wald chi-square = 31.7, P < 0.001) and leptin (Wald chi-square = 21.1, P < 0.001)." (PMID 29636702, 2018). "In this study, a nearly statistically significant interaction between leptin and CRP was observed in men with abdominal obesity." (PMID 26632325, 2016). "In contrast, individuals with abdominal obesity cardiometabolically abnormal exhibited significantly higher levels of hs-CRP, IL-18, chemerin, and leptin, and lower levels of adiponectin and CAG-Ruminococcaceae compared to those with abdominal obesity cardiometabolically healthy and adequate waist." (PMID 39940942, 2025). "Furthermore, central obesity, which BRI specifically targets, induces a chronic inflammatory state characterized by abnormal adipokine profiles, including leptin, adiponectin, and resistance." (PMID 40612321, 2025). "After assessment of multicollinearity, univariate logistic analyses evaluating associations between prevalent hand OA and BMI, increased VFA, central obesity, triglycerides, HDL-cholesterol, LDL-cholesterol, and S-leptin were performed for women and men separately." (PMID 39578778, 2024). "• Diabetic-exposed offspring had higher BMI, waist circumference and body fat, increased general and central obesity at 9–11 years old. • BMI of O-GDM was 0.89 kg/m2 greater than offspring before their mothers got GDM • O-GDM and O-T1DM had more leptin, less adiponectin and FGF21." (PMID 37255932, 2023). "The authors found significantly increased leptin and total adiponectin levels in patients affected by chronic bronchitis with abdominal obesity in comparison with those without abdominal obesity." (PMID 36671433, 2022). "Additionally, leptin, adiponectin, resistin, TNF-α, IL-6, and other metabolic substances are related to the relationship between abdominal obesity and BMD." (PMID 36313427, 2022). "Thus, individuals with central obesity had increased pro-inflammatory adipokines (TNF-α, leptin) and decreased anti-inflammatory adipokines (adiponectin), compared to individuals without central obesity." (PMID 33182462, 2020). "Therefore, this study was designed to determine the role of adipokines (adiponectin, plasminogen activator inhibitor-1, leptin, and TNF-α) in hypertensive Hong Kong Chinese women with established central obesity." (PMID 29636702, 2018). "The 4RF_O had a 133% higher leptin level (mean difference = 9.2 ng/ml, P = 0.023) compared with the 4RF_NO group (i.e., the difference between central obesity and non-central obesity in the 4RF subjects)." (PMID 30114249, 2018). "For instance, a low adiponectin: leptin ratio indicates the severity of MetS in patients with central obesity compared to those without MetS." (PMID 30114249, 2018). "As well,resistin and leptin levels were significantly higher in abdominal obese patientsthan in patients without abdominal obesity or in the control group." (PMID 27627223, 2016). "Adipokines such as leptin, adiponectin, serotonin, resistin and GLP-1, which are secreted by adipocytes or adipose tissues, can result in low-grade inflammation and have important roles in central obesity, IR and T2DM." (PMID 27136447, 2016). "In non-diabetics, leptin levels were partly contributed to increased body fat percentage calculated by waist circumference, an indicator of abdominal obesity." (PMID 23853613, 2013).
Abdominal obesity (continued). "Waist to hip ratio, an indicator of abdominal obesity did exhibit negative significant correlation with leptin in the total study subjects(r = -0.352, P = 0.001)." (PMID 23853613, 2013). "The mean leptin level was higher in boys and in the group with central obesity, but was not significant." (PMID 17721641, 2007). "Although abdominal obesity did not retain statistical significance after adjustment, lifestyle, and occupational factors—particularly shift work and physical activity—appeared to modulate leptin concentrations." (PMID 41439942, 2025). "Although women with abdominal obesity exhibited a higher mean serum leptin concentration (45.2 ng/mL) than those without abdominal obesity (23.8 ng/mL; p < 0.001), this association was not statistically significant after multivariate adjustment (PR = 1.10; 95% CI: 0.97–1.24; p = 0.14)." (PMID 41439942, 2025). "Second, we did not measure hormones or laboratory indexes (e.g., ghrelin, leptin, insulin resistance, or sympathoadrenal activity), which might be the mediator between sleep quality and central obesity." (PMID 34348705, 2021). "The level of leptin depended only on the presence of abdominal obesity, but not dementia status." (PMID 28421328, 2017). "Similarly, in our study we observed significantly lower serum leptin level in whole dementia group in comparison with control subjects only in individuals without abdominal obesity." (PMID 28421328, 2017). "This is consistent with a study that demonstrated that palmitoleic acid was positively related to abdominal obesity in children, possibly because the activation of SCD1 is not sufficiently suppressed by leptin." (PMID 41401179, 2025). "No strong interaction between leptin and CRP was suggested, although among men with abdominal obesity, interaction approached statistical significance (P = 0.07)." (PMID 26632325, 2016). "Also, women with central obesity had higher circulatory PAI-1 and leptin concentrations than their non-obese counterparts." (PMID 29636702, 2018).